TAP1 (transporter 1, ATP binding cassette subfamily B member)
Diseases named in the same sentence as TAP1 in open-access papers (continued):
Sharing a sentence is not in itself a finding about the gene and the disease.
gastric adenocarcinoma (2 papers, 2021 to 2025). "Increased TAP1 expression in gastric adenocarcinoma has independently been demonstrated to enhance the efficacy of checkpoint inhibitor therapy." (PMID 41225774, 2025). "The results showed that compared with normal tissues, tissues of various cancers, including head and neck squamous cell (HNSC), kidney renal clear cell carcinoma (KIRC), and stomach adenocarcinoma (STAD), showed increased levels of TAP1 expression." (PMID 34957213, 2021).
lupus (2 papers, 2013 to 2020). "However, the acceleration in mortality in BXSB.Yaa mice rendered deficient in H-2K/D, Tap1, or CD8α was not as profound as that observed in β2m° BXSB.Yaa mice, suggesting that more than one mechanism likely accounts for the protective effect of β2m in lupus." (PMID 23531237, 2013).
medulloblastoma (2 papers, 2009 to 2023). A malignant, invasive embryonal neoplasm arising from the cerebellum. "We therefore analyzed HLA heavy chains, β2m, TAP1, TAP2 and CD45 intracellular and/or cell surface expression using medulloblastoma tissue microarrays." (PMID 19594892, 2009). "We investigated expression of four essential components of MHC class I (heavy chain, β2m, TAP1 and TAP2) in 10 medulloblastoma mRNA samples, a tissue microarray containing 139 medulloblastoma tissues and 3 medulloblastoma cell lines." (PMID 19594892, 2009). "The expression of the essential components of the MHC class I antigen-processing machinery: HLA heavy chains (A and B), β2m, TAP1 and TAP2 was first evaluated using RNA from ten frozen medulloblastoma specimens." (PMID 19594892, 2009). "Therefore, contamination by infiltrating peripheral white blood cells cannot account for positive heavy chain, TAP1, TAP2 and β2m staining in most of these cases and MHC class I expression appears to be genuinely derived from medulloblastoma cells." (PMID 19594892, 2009).
mesothelioma (2 papers, 2021 to 2023). A usually malignant and aggressive neoplasm of the mesothelium which is often associated with exposure to asbestos. "High levels of TAP1 expression were related with shorter DFS in KIRP (HR = 1.00, p < 0.0001), mesothelioma (MESO) (HR = 1.00, p = 0.0069), and PAAD (HR = 1.00, p = 0.0087)." (PMID 34957213, 2021).
metastatic melanoma (2 papers, 2016 to 2021). A melanoma that has spread from its primary site to another anatomic site. "The observed benefit of IFNα treatment could be mediated by the shown dual effect of TAP1 upregulation in antigen presenting cells on the one hand, and of TAP1 upregulation in ‘silent’ metastatic melanoma cells on the other hand." (PMID 26735690, 2016). "Combination of IFNα with additional vaccination strategies for patients with high IFNα-induced TAP1 expression in PBMCs could be regarded as an option for metastatic melanoma patients." (PMID 26735690, 2016). "The observed benefit of IFNα treatment could be mediated by the shown dual effect of increased TAP1 expression on the one hand in antigen presenting cells and on the other hand in ‘silent’ metastatic melanoma cells." (PMID 26735690, 2016).
nasopharyngeal carcinoma (2 papers, 2015 to 2020). A carcinoma arising from the nasopharyngeal epithelium. "EBV-encoded miRNAs have been reported to downregulate TAP1, TAP2, and ERAP2 mRNA in infected primary B cells, and the TAP2 mRNA was similarly reduced in EBV-associated nasopharyngeal carcinomas." (PMID 32098275, 2020). "In addition, G allele at TAP1 Codon 637 is associated with nasopharyngeal carcinoma (NPC) in Han population in Yunnan, China (OR, 1.88; 95 % CI, 1.35–2.82; P < 0.001), and EBV pathogenesis in NPC might be facilitated by polymorphisms in the TAP1 proteins." (PMID 26205887, 2015).
pulmonary TB (2 papers, 2021 to 2023). "Several studies have shown that abnormalities in the TAP1 gene are closely associated with pulmonary TB." (PMID 37340462, 2023).
rectum adenocarcinoma (2 papers, 2021 to 2023). An adenocarcinoma arising from the rectum. "The results showed that TAP1 was positively related to neoantigens in OC, CESC, LUAD, BRCA, SKCM, and LGG (p < 0.05), whereas it was negatively correlated in COAD and rectum adenocarcinoma (READ)." (PMID 34957213, 2021).
renal carcinoma (2 papers, 2012 to 2021). A carcinoma arising from the epithelium of the renal parenchyma or the renal pelvis. "A differential TAP1 expression has been linked to the liver and renal cancer." (PMID 34047812, 2021).
adult T-cell leukemia/lymphoma (1 paper, 2025). A peripheral (mature) T-cell neoplasm linked to the human T-cell leukemia virus type 1 (HTLV-1), adult T-cell leukemia/lymphoma is endemic in several regions of the world, in particular Japan, the Caribbean, and parts of Central Africa. "Similar alterations have also been reported in extranodal NK/T cell lymphomas (ENKTL), where mutations in HLA-A, β2M, and TAP1 correlate with more advanced disease stage, while approximately 50% of cases of adult T cell leukemia/lymphoma (ATLL) also harbor HLA Class 1 and/or β2M mutations." (PMID 41295262, 2025).
Arthritis (1 paper, 2023). Inflammation of a joint. "Among them, AREG, BPI and TAP1 genes showed an increased expression in arthritis participants." (PMID 38022684, 2023).
atopic dermatitis (1 paper, 2021). "In summary, we found interesting associations of polymorphisms of immunoproteasome components LMP2 and LMP7 as well as of the peptide transporter component TAP1 with susceptibility to atopic dermatitis or with its clinical features." (PMID 33920176, 2021).
autoimmune pancreatitis (1 paper, 2012). "Our study showed that TAP1 and LMP2 expression also increased, which suggested that the presence of excess host dsDNA due to tissue injury might induce the abnormal MHC expression observed in patients with both chronic and autoimmune pancreatitis." (PMID 22550608, 2012).
Autoimmunity (1 paper, 2014). The occurrence of an immune reaction against the organism's own cells or tissues. "Some peptides transported by mutated TAP1 gene products might cause the expression deficiency of MHC I molecules, which resulted in the spontaneous termination of immune tolerance, launched the autoimmunity process and caused the destruction of pancreas islet β cells." (PMID 24655325, 2014).
biliary atresia (1 paper, 2020). A rare, biliary tract disease characterized by progressive obliterative cholangiopathy of the intra- and extrahepatic bile ducts, occurring in the embryonic/ perinatal period, leading to severe and persistent neonatal jaundice and acholic stool. "Interestingly, this atlas unveiled that ABCB2/TAP1 may have TAP2‐independent functions in the brain and that biliary atresia (BA) and control livers have quite different ABC transporter profiles." (PMID 33128234, 2020).
bronchiectasis (1 paper, 2025). Segmental, irreversible dilation of the bronchial tree resulting in the accumulation of secretions which leads to obstruction. "We found that chronic necrotizing granulomatous skin lesions and childhood-onset bronchiectasis were common but not universal clinical features of TAP1, TAP2, TAPBP, and B2M deficiency." (PMID 41298860, 2025).
chronic hepatitis C infection (1 paper, 2014). "In contrast, multidrug-resistant human cancer cell lines and flaviviruses such as hepatitis C virus may upregulate MHC-I in parallel with TAP1 to evade innate NK cell attacks for the establishment of multidrug resistance and chronic hepatitis C infection." (PMID 25143665, 2014).
cyst (1 paper, 2019). A sac-like closed membranous structure that may be empty or contain fluid or amorphous material. "T. gondii interaction with TAP1 and TAP2 could block antigen processing to help hide the cyst during chronic infection or it might assist in nutrient acquisition across the cyst wall." (PMID 31726967, 2019).
dengue disease (1 paper, 2015). Dengue fever (DF), caused by dengue virus, is an arboviral disease characterized by an initial non-specific febrile illness that can sometimes progress to more severe forms manifesting capillary leakage and hemorrhage (dengue hemorrhagic fever, or DHF) and shock (dengue shock syndrome, or DSS). "Polymorphisms of the TAP1 and TAP2 genes could be directly associated with the risk of developing dengue disease among the primary-infected individuals." (PMID 26645066, 2015). "Both TAP1 and TAP2 are located within the MHC class II region and homozygosity of the TAP1 at position 1333 and 1637 and for TAP2 at position 2379, respectively, was found to protect against developing severe forms of dengue." (PMID 26645066, 2015).
fibrosarcoma (1 paper, 2022). A malignant mesenchymal fibroblastic neoplasm affecting the soft tissue and bone. "Next, we examined tumor infiltrating NK cells from the MHC-Ilow tumor cell line MTAP1A, which is a fibrosarcoma generated from the skin of a Tap1-deficient mouse." (PMID 36185379, 2022).
gynecological cancer (1 paper, 2021). "Additionally, we wanted to understand the potential role of TAP1 in CC, which was another common gynecological cancer." (PMID 34957213, 2021).
HIV-1 infection (1 paper, 2020). The type species of lentivirus and the etiologic agent of acquired immunodeficiency syndrome (AIDS). "To determine the correlation between HIV-1 infection and the TAP1 and TAP2 genes polymorphisms, we performed PCR–RFLP assay of these genes in 500 HIV-1 seropositives and the matched seronegative individuals." (PMID 31732831, 2020). "On the other hand, no significant TAP1(C/T intron 7) gene association with the risk of (resistance/susceptibility) to HIV-1 infection was identified." (PMID 31732831, 2020). "The present study set out with the aim of examining the distribution of SNPs in the two MHC-II encoded TAP1 and TAPS 2 genes in North Indians and evaluating whether polymorphisms in these genes are associated with the risk of HIV-1 infection and disease outcome when compared with the controls." (PMID 31732831, 2020).
Hypertension (1 paper, 2024). The presence of chronic increased pressure in the systemic arterial system. "The transport associated with antigen processing 1 (TAP1) gene polymorphism at codon 637 is associated with hypertension with the GG genotype being linked to higher SBP and DBP." (PMID 39258111, 2024). "However, the exact biological role of TAP1 in the pathophysiology of hypertension is not yet fully understood." (PMID 39258111, 2024).
influenza (1 paper, 2020). An acute viral infection of the respiratory tract, occurring in isolated cases, in epidemics, or in pandemics; it is caused by serologically different strains of viruses (influenzaviruses) designated A, B, and C, has a 3-day incubation period, and usually lasts for 3 to 10 days. "STAT1, TAP1, PSMB9, and PSME2, which are up-regulated preferentially by IFN-γ, were overexpressed only in influenza-specific cluster 1 (blue)." (PMID 32651212, 2020).
Insulin resistance (1 paper, 2017). Increased resistance towards insulin, that is, diminished effectiveness of insulin in reducing blood glucose levels. "Besides PTPN1 and STAT5A, some other genes like FASN, TAP1, which are also involved in insulin resistance, have close relationship with MCAT." (PMID 29088862, 2017).
intraepithelial neoplasia (1 paper, 2025). A precancerous neoplastic process that affects the squamous, glandular, or transitional cell epithelium without evidence of invasion. "Notably, TAP1 gene polymorphisms (I333V and D637G) in MB were linked to a reduced risk of high-grade intraepithelial neoplasia, offering actionable insights for clinical management and resource allocation." (PMID 40909174, 2025).
liver cancer (1 paper, 2021). An epithelial or non-epithelial malignant neoplasm that arises from the liver. "TAP1 expression is increased multi-fold times in patients affected with the hepatitis C virus, which is a significant factor of liver cancer." (PMID 34047812, 2021). "For in lower TAP1 expression group (n= 203 and n= 228 respectively) on KM plotter for liver cancer high survival ratio was reported in case of OS and RFS, respectively, compared to the higher expression of the counterparts (n =161 and n = 88, respectively)." (PMID 34047812, 2021).
lumbar disc herniation (1 paper, 2023). "Immunohistochemical staining of PSMB9, STAT1, and TAP1 was performed in 5 patients with spinal tuberculosis and 5 patients with lumbar disc herniation." (PMID 37340462, 2023).
lymph node metastasis (1 paper, 2012). "In addition, downregulation of HLA-I, TAP1, LMP7, tapasin, CRT, and ERp57 had an inverse correlation with lymph node metastasis." (PMID 23024775, 2012).
lymphoid cancer (1 paper, 2021). "The expression profiles of 21 cancer cell lines derived from the CCLE dataset showed high expression levels of TAP1 in the kidney, pleura, and lymphoid cancer cell lines." (PMID 34957213, 2021).
lymphopenia (1 paper, 2019). Reduction in the number of lymphocytes. "Isolated CD8 lymphopenia with preserved CD4 counts can be seen with TAP1, TAP2, and ZAP70 defects." (PMID 31572360, 2019).
malaria (1 paper, 2013). Malaria is a serious and sometimes fatal disease caused by a parasite that commonly infects a certain type of mosquito which feeds on humans. "The expression levels of GBP1, GBP2, and TAP1 ranged from 10.6- to 2.8-fold above baseline during early stage of malaria, and the expression level of GBP2 was greater than two-fold change during acute febrile malaria." (PMID 24188121, 2013).
MELAS (1 paper, 2023). "In IRF2 targets, which were significantly enriched in MELAS subjects, Polg mice, and Tfam± MEFs, USP18, TAP1, BST2, IFI35 were consistently increased." (PMID 37208779, 2023).
metastatic carcinoma (1 paper, 2023). A carcinoma which has spread from the original site of growth to another anatomic site. "In this regard, we validated the screening by demonstrating the increase of TAP-1 and MHC-I expression in metastatic carcinoma cells in response to the chemical entities we discovered." (PMID 37256225, 2023). "Curcuphenol significantly increased the expression TAP-1 and MHC-I in metastatic carcinoma cells from both the prostate and lung while at the same time exhibiting low general cytotoxicity." (PMID 37256225, 2023).
Nephroblastoma (1 paper, 2023). An embryonal neoplasm characterized by the presence of epithelial, mesenchymal, and blastema components. "We observed that HLA class I loss was associated in most cases with low transcriptional levels of HLA class I, TAP1/2 and B2M across several tumor types, by RT-qPCR (Taqman assay) using a panel of PDXs, particularly in neuroblastoma, rhabdomyosarcoma, and nephroblastoma." (PMID 38318504, 2023). "Notably, HLA-B, TAP1 and TAP2 transcript levels were lower than the minimum values of control normal tissues (brain and testis) in ~80% of PDXs (32 out of 44), and B2M levels were also low in neuroblastoma, nephroblastoma, and all but one rhabdomyosarcoma tumors." (PMID 38318504, 2023).
osteosarcoma (1 paper, 2023). A usually aggressive malignant bone-forming mesenchymal neoplasm, predominantly affecting adolescents and young adults. "Furthermore, 49 (10.6%) tumors had LOH affecting APP gene(s) in the HLA region (TAP1/2, TAPBP, PSMB8/9, HSPA1A-L), including 14 (20.6%) osteosarcoma and five (22.7%) GBM cases with LOH in both TAP1 and TAP2." (PMID 38318504, 2023).
prostate tumour (1 paper, 2018). "Metastatic prostate tumour cells containing a green fluorescence protein (GFP) reporter gene under the TAP1 promoter (LMD+pTAP1/GFP) were used as the target cells for CTL-mediated killing." (PMID 29440650, 2018).
Rotavirus infection (1 paper, 2017). Infection with any of the rotaviruses. "Of interest, several IFN inducible genes (OAS1, MX1, IL18, IITP3, TAP1, and RSAD2) as well as several cytokines and chemokines (CCL5, CXCL10, CXCL11, IL8, and CCL15) were upregulated by rotavirus infection." (PMID 28210256, 2017).
rubella infection (1 paper, 2025). "Unfortunately, to date, no therapeutic approach was consistently successful against chronic rubella infection, except hematopoietic stem cell transplantation, including in one patient with concomitant TAP1 and TAP2 deficiency." (PMID 41531537, 2025). "With two previous isolated reports, our findings suggest that inherited TAP1 and TAP2 deficiencies specifically predispose to skin RuV infection; they should not be vaccinated with live-attenuated rubella vaccines." (PMID 41531537, 2025).
sarcoidosis (1 paper, 2022). Sarcoidosis is a multisystemic disorder of unknown cause characterized by the formation of immune granulomas in involved organs. "Non-MHC genes, TAP1, and TAP2, encoding the transporter associated with antigen processing, which participate in the antigen processing pathways prior to its presentation, are also interesting candidates and have been observed to be upregulated in sarcoidosis." (PMID 36203777, 2022).
Sepsis (1 paper, 2022). Sepsis is defined as life-threatening organ dysfunction caused by a dysregulated host response to infection. "Results of qRT-PCR validated the higher expression level of B2M as well as lower expression level of HLA-DQA1, HLA-DPA1, TAP1, and TAP2 in sepsis samples compared to control samples." (PMID 35685286, 2022). "Results of qRT-PCR validated the higher expression level of B2M as well as lower expression level of HLA-DQA1, HLA-DPA1, TAP1, and TAP2 in sepsis samples compared to control sample." (PMID 35685286, 2022). "Compared with healthy controls, B2M was significantly upregulated in sepsis samples yet the expression level of HLA-DQA1, HLA-DPA1, TAP1, and TAP2 was significantly lower in sepsis specimens." (PMID 35685286, 2022).
teratocarcinoma (1 paper, 2010). A germ cell tumor characterized by the presence of an embryonal carcinoma component and a teratoma component. "Unexpectedly, the NT2 teratocarcinoma cell line shows a low expression of TAP-1 and TAP-2, but express tapasin at normal levels." (PMID 20419139, 2010).
triple-negative breast carcinoma (1 paper, 2022). An invasive breast carcinoma which is negative for expression of estrogen receptor (ER), progesterone receptor (PR), and human epidermal growth factor receptor 2 (HER2). "This complex binds and disrupts the stability of Tap1/2 mRNAs, which encode key components of the antigen-presentation machinery, thereby inhibiting tumor antigen presentation and T-cell activation, leading to immune evasion in triple-negative breast cancer." (PMID 35433434, 2022).
urothelial cell carcinoma (1 paper, 2024). "Our study is one of these few, and, to the best of our knowledge is the first report on TAP1 polymorphisms (I333V and D637G) with urothelial cell carcinoma risks in the Japanese population." (PMID 38357083, 2024). "Results indicate that TAP1 gene polymorphisms and the risk of urothelial cell carcinoma are related in females." (PMID 38357083, 2024). "As a conclusion, according to our study, the G allele of TAP1 polymorphisms (I333V and D637G) was susceptible to urothelial cell carcinoma in females, as we detected some interactions between TAP1 polymorphisms (I333V and D637G) and gender." (PMID 38357083, 2024). "Therefore, we decided to investigate the association between urothelial cell carcinoma and two polymorphisms of the TAP1 gene (I333V and D637G)." (PMID 38357083, 2024).